ATP6V1G2 (ATPase H+ transporting V1 subunit G2)
Description:
Subunit of the V1 complex of vacuolar(H+)-ATPase (V-ATPase), a multisubunit enzyme composed of a peripheral complex (V1) that hydrolyzes ATP and a membrane integral complex (V0) that translocates protons. V-ATPase is responsible for acidifying and maintaining the pH of intracellular compartments and in some cell types, is targeted to the plasma membrane, where it is responsible for acidifying the extracellular environment.
Synonyms: ATP6G; ATP6G2; NG38; Vma10; Em:AC004181.3
Tractability: Antibody: UniProt places it where antibodies can reach, with high confidence. PROTAC: ubiquitination databases record sites on it; its protein half-life has been measured.
Gene: Protein-coding gene on chromosome 6 (31,544,444 to 31,548,427, reverse strand). Ensembl gene ENSG00000213760.
Subcellular location: Melanosome; Cytoplasmic vesicle, clathrin-coated vesicle membrane
Pathways (Reactome):
Transport of small molecules: Ion channel transport; Transferrin endocytosis and recycling
Cellular responses to stimuli: Amino acids regulate mTORC1
Immune System: ROS and RNS production in phagocytes
Signal Transduction: Insulin receptor recycling
Gene Ontology:
Molecular function: protein binding; proton-transporting ATPase activity, rotational mechanism
Biological process: regulation of macroautophagy; synaptic vesicle lumen acidification; proton transmembrane transport
Cellular component: melanosome; cytosol; synaptic vesicle membrane; vacuolar proton-transporting V-type ATPase, V1 domain; clathrin-coated vesicle membrane; extrinsic component of synaptic vesicle membrane; vacuolar proton-transporting V-type ATPase complex
Genetic constraint (gnomAD): Loss-of-function variants: 14 observed, 19.02 expected, observed/expected ratio (o/e) 0.74, 90% interval 0.49 to 1.15. The upper end of that interval is the gene's LOEUF score, 1.15, which puts it in group 5 of 6, group 1 being the genes least tolerant of losing a copy. Missense variants: 112 observed, 161.58 expected, observed/expected ratio (o/e) 0.69, 90% interval 0.59 to 0.81. Synonymous variants: 57 observed, 58.13 expected, observed/expected ratio (o/e) 0.98, 90% interval 0.79 to 1.22.
Homologues: Orthologues: macaque ATP6V1G2 (99% identical), pig ATP6V1G2 (98% identical), rat Atp6v1g2 (97% identical), guinea pig ATP6V1G2 (96% identical), mouse Atp6v1g2 (95% identical), chimpanzee ATP6V1G2 (81% identical), rabbit ATP6V1G2 (78% identical), Caenorhabditis elegans vha-10 (48% identical), Drosophila melanogaster Vha13 (47% identical). Paralogues in human: ATP6V1G1 (64% identical), ATP6V1G3 (54% identical).
Diseases named in the same sentence as ATP6V1G2 in open-access papers:
ATP6V1G2 is named in the same sentence as 24 diseases in open-access papers, as found by Europe PMC text mining. Sharing a sentence is not in itself a finding about the gene and the disease. The quoted sentences say what the papers report.
glioma (3 papers, 2022 to 2024). A benign or malignant brain and spinal cord tumor that arises from glial cells (astrocytes, oligodendrocytes, ependymal cells). "Also, K–M curves in 313 gliomas sample through CGGA database showed that low expression of ATP6V1G2, GABARAPL1 and GOT1 was associated with poor prognosis, which was consistent with the results from the TCGA database." (PMID 35896732, 2022). "ATP6V1G2 of the V-ATPase that were related to glioma patient prognosis and was ferroptosis-related to glioma." (PMID 38698303, 2024). "For example, the CRY2, ALDH5A1, and ATP6V1G2 tumor suppressor genes are involved in osteosarcoma, ovarian cancer, and glioma, respectively." (PMID 38552216, 2024). "Internal validation of the prognostic value for ATP6V1G2 was performed using 669 glioma samples from TCGA, with the time-dependent ROC curve showing high predictive efficacy of ATP6V1G2." (PMID 35896732, 2022). "Glioma patients with low ATP6V1G2 expression tended to suffer a shorter OS than those with high ATP6V1G2 expression." (PMID 35896732, 2022). "External validation was achieved using 313 glioma samples from CGGA, and the time-dependent ROC curve similarly validated the efficient predictive efficacy of ATP6V1G2 on glioma prognosis." (PMID 35896732, 2022). "This is the first study to confirm that ATP6V1G2 is tumor-related and may affect the prognosis of glioma patients." (PMID 35896732, 2022). "ATP6V1G2 might be an independent prognostic factor and, as such, a high-precision prognostic model of glioma was constructed." (PMID 35896732, 2022). "Combined with their high expression in non-glioma samples, we speculated that ATP6V1G2, GABARAPL1, and GOT1 might be suppressor genes for glioma." (PMID 35896732, 2022). "In the construction of the model, we demonstrated that ATP6V1G2 could act as an independent prognostic factor for glioma patients and incorporated it into the prognostic model." (PMID 35896732, 2022). "Additionally, in terms of ATP6V1G2, the expression relationship between ATP6V1G2 and multiple DNA methylation probes demonstrated significant negative correlations (all P < 0.05, r < − 0.3) in the TCGA database of glioma samples." (PMID 35896732, 2022). "Besides, the significant negative correlations between the expression of ATP6V1G2 and multiple DNA methylation probes in glioma suggested that ATP6V1G2 might play an active role in the DNA methylation process." (PMID 35896732, 2022). "Overall, the expression of ATP6V1G2, GABARAPL1 and GOT1 was significantly elevated in low-grade glioma compared to high-grade glioma." (PMID 35896732, 2022). "The expression of ATP6V1G2, GABARAPL1, GOT1 along with common glioma characteristics (age, gender, race, tumor grade, 1p/19q status, IDH status) were included in the univariate Cox regression analysis." (PMID 35896732, 2022). "The results implied that advanced age, high-grade tumor, 1p/19q non-codeletion, IDH-non mutation, low expression of ATP6V1G2, GABARAPL1 and GOT1 might be poor prognostic factors for glioma patients." (PMID 35896732, 2022).
asthma (1 paper, 2024). "With respect to increased risk of asthma, blood genes again had the largest relative effect sizes in males (BAG6, CCNG, CRAT, PTPA, and FAM89B), with female training genes exhibiting the largest effects in ATP6V1G2 in the vastus lateralis, ENDOU in white adipose, and CCNF in blood." (PMID 38693125, 2024).
autoimmune disease (1 paper, 2021). A disorder resulting from loss of function or tissue destruction of an organ or multiple organs, arising from humoral or cellular immune responses of the individual to their own tissue constituents. "Other immune diseases, such as RA (hsa05323) were associated with HLA-DQA1 and ATP6V1G2 locus and it was also revealed that autoimmune diseases may coexist with NMOSD or share common pathological pathways." (PMID 34367251, 2021).
colorectal cancer (1 paper, 2021). A primary or metastatic malignant neoplasm that affects the colon or rectum. "For example, ATP6V1G2 is a ferroptosis-related gene that plays a primary role in metabolism and oxidative stress and is defined as a colorectal cancer prognosis biomarker." (PMID 35003220, 2021).
Crohn disease (1 paper, 2025). A gastrointestinal disorder characterized by chronic inflammation involving all layers of the intestinal wall, noncaseating granulomas affecting the intestinal wall and regional lymph nodes, and transmural fibrosis. "By integrating multi-omics approaches, this study reveals a crucial connection between ferroptosis and immune microenvironment dysregulation in Crohn’s disease (CD), identifying seven hub ferroptosis-related differentially expressed genes (FEDGs): SCD, ATF4, SAT1, RPL8, MUC1, MTDH, and ATP6V1G2." (PMID 41515900, 2025).
Huntington disease (1 paper, 2025). Huntington disease (HD) is a rare neurodegenerative disorder of the central nervous system characterized by unwanted choreatic movements, behavioral and psychiatric disturbances and dementia. "Studies have shown that ATP6V1G2 is significantly downregulated in AD, as well as in Parkinson's disease (PD) and Huntington's disease (HD), a finding that aligns with our research." (PMID 40021385, 2025).
melanoma (1 paper, 2025). A malignant, usually aggressive tumor composed of atypical, neoplastic melanocytes. "Among these, VSNL1, ATP6V1G2, and DNM1 exhibited significant downregulation in both PD patients and melanoma patients, suggests a common molecular mechanism underlying these two conditions." (PMID 40066251, 2025). "ATP6V1G2, a subunit of the V-ATPase, is involved in the dysregulated pH homeostasis observed in melanoma." (PMID 40066251, 2025). "A total of 41 overlapping DEGs were identified, including VSNL1, ATP6V1G2, and DNM1, which were significantly down-regulated in both PD and melanoma patients." (PMID 40066251, 2025). "Retinoic acid was found to have binding affinity for VSNL1, ATP6V1G2, and DNM1, indicating its potential as a therapeutic agent for PD and melanoma." (PMID 40066251, 2025). "In the quest for potential anti-PD and anti-melanoma medications, drugs capable of targeting VSNL1, ATP6V1G2, and DNM1 were identified through screening in the DsigDB database." (PMID 40066251, 2025).
Paget's disease of the bone (1 paper, 2022). "Tiludronic acid (DB01133), an inhibitor of ATP6V1D, ATP6V1G2, and ATP6V1H, is used for the treatment of Paget's disease of the bone." (PMID 35875800, 2022).
psoriasis (1 paper, 2024). An autoimmune condition characterized by red, well-delineated plaques with silvery scales that are usually on the extensor surfaces and scalp. "ATP6V1G2 is situated in the HLA region, akin to the psoriasis susceptibility region containing HLA-C, such as TNF." (PMID 39026678, 2024).
tumor (3 papers, 2021 to 2022). "The statistically significant results (age, tumor grade, IDH status, ATP6V1G2 expression) of the multivariate Cox regression analysis were incorporated into the construction of the nomogram." (PMID 35896732, 2022).
infection (2 papers, 2007 to 2021). The state of being infected such as from the introduction of a foreign agent such as serum, vaccine, antigenic substance or organism. "The expression of Uqcrq, Cox4i1, Ndufb8, Atp6v1g2 and Atp5b involved in oxidative phosphorylation was upregulated in CM-R mice on day 2 post-infection, suggesting that cerebral oxidative metabolism may be stimulated by PbA infection in CM-R mice." (PMID 18062806, 2007).
immune disease (1 paper, 2021). "In KEGG, genes associated with immune disease and system include HLA-DQA1, HIST1H2BL, HIST1H2AL, C2, CFB, HSPA1A, TAP2, HIST1H3Jand ATP6V1G2." (PMID 34367251, 2021).
neurodegenerative disease (1 paper, 2025). A disorder of the central nervous system characterized by gradual and progressive loss of neural tissue and neurologic function. "Dysregulation of ATP6V1G2 has been associated with neurodegenerative diseases." (PMID 40066251, 2025).
ATP6V1G2 also shares sentences with these, for which no sentence is quoted: cancer (3 papers); cardiovascular disease (2); rheumatoid arthritis (2); diabetic cardiomyopathy (1); gastric cancer (1); Obesity (1); opsoclonus-myoclonus syndrome (1); osteoporosis (1); osteosarcoma (1); ovarian carcinoma (1); Parkinson disease (1).